PDGFRA (platelet derived growth factor receptor alpha)
Diseases named in the same sentence as PDGFRA in open-access papers (continued):
Sharing a sentence is not in itself a finding about the gene and the disease.
glioma (continued). "Pathological and clinical parameters of gliomas with varying extent of PDGFRA expression." (PMID 23630597, 2013). "In addition, the phosphorylation of Dock180 at tyrosine 1811 has been demonstrated to occur downstream of PDGFRα in glioma, promoting Rac1 activation and cell invasion, migration, and survival." (PMID 24109588, 2013). "Recently, miR-128 was also shown to target EGFR and PDGFRα in glioma stem cells." (PMID 23690991, 2013). "To study whether FGF2 affects the expression of other gliogenic genes in addition to PDGFRA, we characterized the transcriptome profiles in two glioma cell lines cultured under the same conditions as above with or without FGF2 support." (PMID 23630597, 2013). "Thus, FGF2 appears to be a key growth factor involved in regulating PDGFRA expression in glioma cells." (PMID 23630597, 2013). "Fibroblast growth factor 2 (FGF2) was able to maintain PDGFRA expression in glioma cells." (PMID 23630597, 2013). "In conclusion, the role of PDGF-A that was shown in this model system is consistent with the PDGFRA overexpression observed in human low-grade gliomas, whereas the role of PDGF-B was to promote the full-blown vascular proliferations that are characteristic of human GBs." (PMID 22509804, 2012). "PDGFRA expression was examined in a larger number of glioma samples of different malignancy grades." (PMID 22509804, 2012). "Its gene expression profile is enriched for the proneural and PDGFRA-amplified glioma signatures." (PMID 22389665, 2012). "Therefore the exact relationship between our PDGF proteomic class, the PDGFRA co-cluster, and gliomas harboring Proneural signature is unclear and will need to be further investigated." (PMID 19915670, 2009). "Taken together, our results could provide in the future a molecular basis for PDGFRA-targeted therapies in gliomas." (PMID 19707201, 2009). "Clinical trials evaluating the efficacy of anti-PDGFRA therapies on gliomas are ongoing." (PMID 19707201, 2009). "Another common alteration in diffuse astrocytomas is overexpression of the platelet-derived growth factor receptor alpha (PDGFRA) and its ligand PDGFalpha; PDGFRA amplification, however, is restricted to a small subset of high-grade gliomas, in particular glioblastomas." (PMID 19333441, 2009). "Interestingly, both lines harboured genetic alterations reminiscent of high grade gliomas in humans - including the archetypal 4q12 amplification spanning PDGFRA and KIT in Res259, and PTEN deletion in Res186." (PMID 19365568, 2009). "It has been suggested that activation of PDGFRA signalling, directly or indirectly through creating a favourable microenvironment niche, can contribute to the transformation of neural stem/progenitor cells into glioma tumours." (PMID 19707201, 2009). "In addition to well-established PDGFRα expression, we identified that the majority of low-grade astrocytomas and high-grade gliomas concomitantly express multiple markers of glial progenitor cells such as A2B5 and O4." (PMID 18398462, 2008). "The expression of GFAP and these oligodendrocyte progenitor surface markers suggests that along the oligodendrocyte lineage differentiation hierarchy, A2B5+/PDGFRα+ glioma cells were compromised in differentiation downstream of A2B5/O4, but upstream of the O1 stage." (PMID 18398462, 2008). "By dissecting the intricate PDGFRA-mediated signaling network, we highlight critical targets and outline strategies for developing precision-oriented, individualized immunotherapeutic interventions, aiming to significantly improve outcomes for patients with gliomas." (PMID 41847712, 2026). "Additionally, the top Kyoto Encyclopedia of Genes and Genomes (KEGG) pathways associated with COL1A1, ITGB1, THY1, and PDGFRA genes included pathways such as “ECM receptor interaction, leukocyte transendothelial migration, platelet activation, focal adhesion, and glioma” among others." (PMID 40817072, 2025).
glioma (continued). "Indeed, total IDH1 (IDH1wt and IDH1R132H) protein levels were higher in mIDH cell lines when compared to wtIDH cells and IDH1 and IDH2 expression was highest in PDGFRA+ tumor cells, which are the majority of glioma cells in mIDH tumors and a small percentage of GSCs in wtIDH tumors." (PMID 40060572, 2025). "And in PDGFRA driven glioma, inhibition of IGFBP7 may improve the efficacy of PDGFRA inhibitors." (PMID 36043552, 2023). "Moreover, circCDK14 reduced glioma cells' sensitivity to Fp by regulating the expression of PDGFRA." (PMID 35002529, 2022). "Whether PARP-1 plays a similar role in gliomas and other PDGFRα-driven tumors is unclear." (PMID 33922595, 2021). "Dasatinib was ineffective in phase I/II trials in recurrent GB, even in combination with bevacizumab or lomustine, which could be due to a proposed active efflux mechanism; however, efficacy of dasatinib treatment of PDGFRα-driven high grade gliomas could be enhanced with everolimus." (PMID 34209513, 2021). "Because all DCGs without H3 K27M mutation in this study were clustered in the “RTK I” methylation group, we next examined whether DCGs in this “RTK I” group have a similar gene expression pattern to other gliomas in this group, which often have PDGFRA amplification." (PMID 28852847, 2017). "Consistent with NS-culture-derived glioma cells with high invasiveness, genes highly expressed in 51A were those encoding markers of neural stem/precursor cells (NANOG, POU3F2, POU5F1, and SALL2), and pro-invasive proteins (AGAP2, EPHA2, FOXM1, PDGFRA, and TNC)." (PMID 29113349, 2017). "Concurrent amplifications of EGFR and PDGFRA have been reported in up to 5% of glioblastoma (GBM) and it remains unclear why such independent amplification events, and associated receptor overexpression, would be adaptive during glioma evolution." (PMID 28831081, 2017). "Furthermore PDGFRA represents an oncogene that is involved in cancer cell survival including pediatric glial tumours as well as resistance to chemotherapy and radiation therapy, and its inhibition may sensitize tumors to DNA damaging agents." (PMID 26599335, 2015). "A surface location of PDGFRA is required for glioma cells to sense its microenvironment and down-regulation of surface expression of PDGFRA or other RTKs may be a successful approach to inhibit glioma cell growth." (PMID 24489888, 2014). "Moreover, this U0126 induced reduction of surface PDGFRA occurred in all tested glioma cell lines." (PMID 24489888, 2014). "Furthermore, using real-time RT-PCR and western-blot analyses in the glioma cell line #2 with high surface PDGFRA expression, we demonstrated that in cells with significant decline of the surface PDGFRA expression, no measurable reduction of PDGFRA transcript and protein was detected." (PMID 24489888, 2014). "Interestingly, immunohistochemistry staining of the proliferation marker Ki67 showed that the glioma cell proliferation was about three-fold higher in tissues with high surface PDGFRA expression compared with those with tissues with low surface PDGFRA expression (p<0.001, n = 6)." (PMID 24489888, 2014). "Thus, gliomas with high levels of PDGFRA expression and gliomas with high levels of EGFR amplification and expression may originate from different cellular and genetic origins." (PMID 24489888, 2014).
glioma (continued). "Importantly, Pax3 is regionally expressed in human glioma as well, with high PAX3 mRNA characterizing 40% of human BSG, revealing a subset of tumors that significantly associates with PDGFRA alterations, amplifications of cell cycle regulatory genes, and is exclusive of ACVR1 mutations." (PMID 25330836, 2014). "However, all morphological subtypes were represented among gliomas with enriched PDGFRA expression." (PMID 23630597, 2013). "Next, we hypothesized that PDGFRA overexpression in glioma cells is niche factor dependent." (PMID 23630597, 2013). "Thus, although further in-depth characterizations on their transcriptomic and genomic profiles are required, gliomas with varying extent of PDGFRA expression could represent different molecular subtypes that respond differently to FGF2 signaling." (PMID 23630597, 2013). "In this report, we hypothesize that PDGFRA expression is regulated by gliogenic factors in gliomas." (PMID 23630597, 2013). "In addition, as secondary gliomas in children have a high frequency of Ink4a-ARF loss and PDGFRα amplifications, PD-0332991 may be particularly suitable for this population." (PMID 24098593, 2013). "We further assessed whether FGF2 can induce PDGFRA expression in glioma cells." (PMID 23630597, 2013). "PDGFRA gene amplification rather than gene mutation may be the underlying genetic mechanism driving PDGFRA overexpression in a portion of gliomas." (PMID 19707201, 2009). "Based on the concurrent expression of PDGFA and PDGFRA in glioblastomas, it could be hypothesised that autocrine/paracrine loops may be present in these tumours, corroborating the importance of this signalling pathway in gliomas." (PMID 19707201, 2009). "PDGFRA and CDK6 amplification were enriched in diffuse hemispheric gliomas when compared to other adult-type gliomas." (PMID 39842935, 2025). "Tumor progenitor populations in high-grade gliomas and oligodendrogliomas often express markers such as Olig2, Nkx2.2, and PDGFRα, supporting the concept that OPC-like cells act as critical drivers of glioma progression." (PMID 41272822, 2025). "As mentioned in the Introduction, PDGFRA and MYCN amplifications were characteristic of some pediatric H3-wildtype high-grade gliomas." (PMID 38201659, 2024). "While these four genes (PDGFA, PDGFRA, CREB1, and PLAT) have been studied individually, our findings highlight their collective significance in glioma." (PMID 39606019, 2024). "Other than NG2 proteoglycan, the vast majority of gliomas express other markers typical for OP, such as Olig-2 and PDGFRα, while NG2 and PDGFRα are key factors for cellular proliferation and motility." (PMID 39057054, 2024). "However, as PDGFRA is not mutated in 100% of H3.3-G34R/V mutant gliomas, perhaps there are different ways that the mutant cells can become gliomas, similar to how PDGFRA reflects an oligodendroglial differentiated type of diffuse intrinsic pontine glioma (DIPG) in contrast to a mesenchymal type." (PMID 37509641, 2023). "GliomaSCAN is a big NGS panel comprising 232 genes for detecting most of the glioma markers, including SNPs, CNVs (1p/19q-codeletion and chr +7/-10), and amplifications (EGFR, PDGFRA)." (PMID 37908227, 2023). "MET is among the top three dysregulated receptor tyrosine kinases (RTKs) in glioma cells, along with EGFR and PDGFRA." (PMID 37214395, 2023). "In contrast, key regulators of OPC specification and maintenance, including MYT1, OLIG2, PDGFRA, PTPRZ1, SMOC1, and SOX8 were hypomethylated in PM gliomas." (PMID 37055795, 2023). "PDGFA/PDGFRA signaling has been shown to induce EMT through stimulation of ZEB1, thereby promoting glioma tumor growth and invasion and GSCS stemness." (PMID 36829235, 2023). "In particular, in this third molecular type fall pleomorphic-xantoastrocytoma (PXA)-like pHGGs, v-myc myelocytomatosis viral-related oncogene (NMYC), platelet-derived growth factor receptor A (PDGFRA), or EGFR amplified gliomas and hypermutant pHGGs." (PMID 35456430, 2022).
glioma (continued). "Human IDH gene mutant gliomas exhibit DNA hypermethylation, which reduces CTCF binding at the PDGFRA oncogene TAD border, eliminating TAD border insulation, and activating the PDGFRA oncogene." (PMID 35509102, 2022). "The results showed that PDGFRA expression are upregulated only in GBM, LGG (Low grade glioma) and PAAD (Pancreatic adenocarcinoma)." (PMID 35002529, 2022). "Hence, the miR-3938/PDGFRA axis may be an excellent candidate of anti-glioma therapy." (PMID 35002529, 2022). "To evaluate protein expression of PDGFRA and EPHA2 using clinical samples of glioma, we collected a 180-case glioma cohort (Cohort-180)." (PMID 35105853, 2022). "There were multiple, cancer type–specific hot spots of junctions located near known oncogenes such as KIT, PDGFRA, EGFR, CDK4, MDM2 (glioma), TMPRSS2, ERG (PCa), FGFR1, and CCDN1 (BrCa)." (PMID 34891161, 2021). "In these “phospho-SFK high” tumours 66% also expressed high PDGFRA or PDGFRB or both, supporting a scenario in which PDGFR signalling contributes to SRC/SFK activation in high-grade gliomas." (PMID 33478100, 2021). "The incidence of PDGFRA amplification increases to 23% in pediatric GBM and 30% in high-grade pediatric gliomas." (PMID 34470658, 2021). "To evaluate the therapeutic effect of PDGFRA inhibition on tumor growth in vivo, we administered Cre (15 mg/kg) or 5% glycerol formal (Gly, solvent) to an orthotopic murine model of GL261 glioma for 7 days." (PMID 32019907, 2020). "In the mouse glioma cell line, IGF1R highly overlapped not only with the OPC marker PDGFRα, but also with those marking proliferation and stemness." (PMID 33173731, 2020). "Here we demonstrate that glioma organoids and PDOXs accurately maintain distinct genetic backgrounds of parental tumors, including gene amplifications of EGFR, PDGFRA, MET, MDM2/4, and CDK4/6, which are difficult to derive and preserve in vitro." (PMID 33009951, 2020). "Although PDGFRA amplification is less common in gliomas than EGFR amplification, PDGFRA gene amplification is found in 11% of GBMs, making it the second most frequent RTK gene amplified in this family of tumors." (PMID 33081688, 2020). "Taken together, these results provide information on CHSY1 expression and its role in glioma progression, and highlight novel insights into the significance of CHSY1 in PDGFRA signaling." (PMID 32019907, 2020). "The EM/PM subtype is another glioma molecular classification based on the coexpression modules of EGFR and PDGFRA." (PMID 33575206, 2020). "These spinal tumors expressed classical glioma markers, such as GFAP, Sox2, Olig2, and PDGFRa, and had a lower proliferative index than the corresponding brain tumors." (PMID 32727536, 2020). "In this study, 47.6% of glioma patients were detected ctDNA including 1p/19q, MDM2, ERBB2, IDH1, CDKN2A, CDK4, PDGFRA, CCNE1, MET." (PMID 32973641, 2020). "The glioma oncogene and PI3K-AKT activator, Pdgfrα, was also a CIS, with an insertional pattern consistent with gene activation." (PMID 32727536, 2020). "Utilization of tissue microarrays of canine glioma for immunohistochemistry has revealed overexpression of EGFR, PDGFRα, IGFBP2 with EGFR expression moderately correlated to Ki67 immunoreactivity." (PMID 31788444, 2019). "The ITH in high-grade glioma was elucidated in a scRNA-seq study through profiling gene expression of single cells in EGFR amplified and PDGFRA amplified tumors." (PMID 31586689, 2019). "The human PDGFRA overexpressing glioma DEG dataset was then compared to the rodent and canine PDGFRA overexpressing glioma DEG datasets separately." (PMID 29352201, 2018).
glioma (continued). "CCAT1 promotes glioma tumourigenesis by sponging miR-181b through its regulation of FGFR3 and PDGFRα." (PMID 29552296, 2018). "As a whole, all these observations are in line with the origin of most gliomas from the subcortical white matter rich in OPCs expressing NG2/CSPG4, PDGFRα, and Olig2." (PMID 30213051, 2018). "PDGF signaling in one of the strongest drivers of glioma initiation and evolution and the PDGF receptor-alpha (PDGFRA) tyrosine kinase is frequently overexpressed in human gliomas." (PMID 29352201, 2018). "The last finding of this research belongs to the regulation of PDGFA/PDGFRα on GOLM1, while GOLM1 was also a key element of PDGFA/PDGFRα-mediated activation of AKT, as well as the progression of glioma cells." (PMID 29282077, 2017). "To investigate the functional relationship between PDGFRα and GOLM1, we examined GOLM1 protein levels in parental and modified glioma cells treated with PDGFA." (PMID 29282077, 2017). "PDGFRA is amplified less frequently in adult HGG, but has been found to carry a worse prognosis in adult anaplastic astrocytoma (WHO grade III glioma)." (PMID 27582545, 2016). "The genomic alterations in EGFR, PDGFRA, NF1, PTEN and PIK3CA were nearly exclusively found in the RMPAhigh gliomas." (PMID 27385209, 2016). "Co-occurrence between amplification of EPHB3 and alterations in PIK3CA (both at chromosome 3q26-3q27), and amplifications in PDGFRA, KIT and KDR (all at 4q12) were also found in a subset of RMPAhigh gliomas, due to their localization in the common amplicons." (PMID 27385209, 2016). "Here, we report that cell surface PDGFRA expression in gliomas is negatively regulated by an ERK-dependent mechanism, resulting in reduced proliferation of glioma cells." (PMID 24489888, 2014). "HCMV induced increased migration of U87 glioma cells to a similar extend as PDGF-AA (20ng/ml) and this effect was significantly reverted by the co-incubation with the 3G3, a PDGFRα blocking antibody." (PMID 24658280, 2014). "First, adult neural stem cells express PDGFRα and proliferate in response to PDGF originating glioma-like hyperplasias." (PMID 24709958, 2014). "In PDGFRA amplified gliomas two genetic rearrangements have been described – a gene fusion between kinase insert domain receptor (KDR) and the PDGRFA gene and PDGFRA (Δ8, 9), an intragenic deletion rearrangement." (PMID 24716189, 2014). "Since HCMV can activate PDGFRα to a similar extent as the natural ligand, we set out to investigate the effects of HCMV on glioma cell stress fibers, which support enhanced tumor cell motility." (PMID 24658280, 2014). "A well-studied cluster on chromosome 4q containing PDGFRA, KIT, and KDR was amplified in glioma and melanomas." (PMID 24874471, 2014). "The ODA14 tumour was selected after quantitative PCR screening of a series of gliomas for amplification of the EGFR,MET,MYC and PDGFRA genes, which are known to be recurrently amplified in these tumours." (PMID 25378339, 2014). "Using large glioma gene expression databases, we found that the expression of both PDGFRA and FGF2 were enriched in low-grade gliomas." (PMID 23630597, 2013). "In large numbers of glioma samples, our results showed that the pattern of FGF2 expression was similar to that of PDGFRA expression." (PMID 23630597, 2013). "However, different mechanisms may account for high-level PDGFRA expression in gliomas." (PMID 23630597, 2013). "We used specific FISH probes independently designed to recognise PDGFRA, KIT and VEGFR2 genes to determine the relative frequencies of gene amplification at chromosome 4q12 in our high grade glioma series." (PMID 23990986, 2013). "The aim of this study was to assess the relative contributions of PDGFRA, KIT and VEGFR2 to high grade glioma tumour biology, in terms of gene amplification and expression in the tumour cells and associated vasculature." (PMID 23990986, 2013).